TNFAIP3 (TNF alpha induced protein 3)
Diseases named in the same sentence as TNFAIP3 in open-access papers (continued):
Sharing a sentence is not in itself a finding about the gene and the disease.
Obesity (4 papers, 2019 to 2025). Accumulation of substantial excess body fat. "Oral consumption of PLX5662, a more brain-penetrant CSF-1R inhibitor than PLX3397, produces no alterations in consummatory behavior or weight gain in mice, while genetic activation of microglia by tumor necrosis factor a-induced protein 3 (TNFAIP3) causes obesity." (PMID 41228515, 2025). "In contrast, intestinal TRM DEGs that were increased in obesity have less enrichment in these pathways and some function as brakes on inflammation (e.g. TNFAIP3, DDX5842)." (PMID 40909804, 2025). "Thus, FBXL20 and TNFAIP3 could be new candidate genes to be studied in the context of obesity." (PMID 37252693, 2023). "PTGS2 and TNFAIP3 were identified as hypomethylated-high-expression genes and FBXL20 as a hypermethylated-low expression gene in SAT of individuals with obesity." (PMID 37252693, 2023). "We considered the three most connective nodes as hub-bottleneck genes: prostaglandin-endoperoxide synthase 2 ( PTGS2 ), tumor necrosis factor α-induced protein 3 ( TNFAIP3 ), and F-box and leucine rich repeat protein 20 ( FBXL20 ), which might play a critical role in obesity." (PMID 37252693, 2023).
Oral ulcer (4 papers, 2011 to 2023). Erosion of the mucous mebrane of the mouth with local excavation of the surface, resulting from the sloughing of inflammatory necrotic tissue. "Patient 41 had also presented with early onset inflammatory bowel disease and oral ulcers and a novel variant in TNFAIP3) gene was found." (PMID 33815380, 2021). "When younger brother also developed recurrent oral ulcers, genetic studies were performed in the index patent and targeted panel revealed a novel variant in Tumor necrosis factor alpha-induced protein 3 (TNFAIP3) gene." (PMID 33815380, 2021). "The identical TNFAIP3 mutation was also found in her father and brother who had suffered from recurrent oral ulcers since childhood." (PMID 32719680, 2020). "TNFAIP3 and ETS1 were significantly associated with most subphenotypes, but none of them showed association with oral ulcers." (PMID 22087647, 2011).
psoriasis vulgaris (4 papers, 2019 to 2024). Plaque psoriasis is the most common presentation of psoriasis. "The loss of up-regulation of TNFAIP3 expression in severe psoriasis vulgaris can be explained by certain epigenetic events that may take place in the TNFAIP3 gene including a 5′ region polymorphism or promoter methylation." (PMID 31120955, 2019). "GWAS identified genetic variations in TNFAIP3 (encoding A20), TNIP1 and FASL, involved in apoptotic and necroptotic cell death regulation, as susceptibility factors for psoriasis vulgaris." (PMID 38649745, 2024). "Since most of our samples are mild to moderate psoriasis vulgaris, some studies have shown that the expression level of TNFAIP3 is negatively correlated with the severity of the disease." (PMID 35277199, 2022). "Moreover, the gene expression of TNFAIP3 was also reduced in peripheral blood mononuclear cells of patients with psoriasis vulgaris." (PMID 34500744, 2021). "Accordingly, the inefficient expression of the TNFAIP3 gene in severe psoriasis vulgaris may be due in part to its aberrant methylation." (PMID 31120955, 2019).
ankylosing spondylitis (3 papers, 2010 to 2024). An autoimmune chronic inflammatory disorder characterized by inflammation in the vertebral joints of the spine and sacroiliac joints. "This study was conducted to clarify the associations of tumor necrosis factor-α induced protein 3 (TNFAIP3) and TNFAIP3-interacting protein 1 (TNIP1) genetic polymorphisms with ankylosing spondylitis (AS) susceptibility." (PMID 31308453, 2019).
autoimmune lymphoproliferative syndrome (3 papers, 2018 to 2021). Autoimmune lymphoproliferative syndrome (ALPS) is a rare, inherited disorder characterized by non-malignant lymphoproliferation, multilineage cytopenias, and a lifelong increased risk of Hodgkin's and non-Hodgkin's lymphoma. "There is also a single case of 7-month-old Japanese child who presented with typical clinical and laboratory features suggestive of autoimmune lymphoproliferative syndrome, but subsequent genetic testing showed heterozygous mutation in TNFAIP3 resulting in HA20 diagnosis." (PMID 30022980, 2018).
Cerebral ischemia (3 papers, 2018 to 2025). Restriction of arterial blood supply to the brain associated with insufficient oxygenation to support the metabolic requirements of the tissue. "In previous studies, we found that the expression of TNFAIP3 in a cerebral ischemia-reperfusion mouse model was significantly reduced." (PMID 34853620, 2021).
Hypertension (3 papers, 2020 to 2022). The presence of chronic increased pressure in the systemic arterial system. "Between carvedilol and timolol there was an overlap of 15 genes, causing an upregulation, among others, of GPER1, PDE4B and TNFAIP3, which are genes directly associated with hypertension." (PMID 35446883, 2022). "Only three of the 23 unique genes replicated, have been directly associated with hypertension (GPER1, PDE4B and TNFAIP3) so far." (PMID 35446883, 2022). "In the case of carvedilol, we showed that, beside genes with well-established association with hypertension (GPER1, PDE4B and TNFAIP3), the drug also affects genes that are only indirectly linked to hypertension due to their effects on artery walls or their role in lipid biosynthesis." (PMID 35446883, 2022).
inflammatory skin disorder (3 papers, 2019 to 2021). "Hence, TNFAIP3 deficiency in keratinocytes leads to inflammatory gene signature in the epidermis and systemic proinflammatory changes and is sufficient to exacerbate inflammatory skin disorders." (PMID 31120955, 2019). "A correlation between RP11-356I2.4 and TNFAIP3 has also previously been observed in the inflammatory skin disorder chronic actinic dermatitis, where both genes were downregulated in comparison to healthy controls." (PMID 33922041, 2021).
intracerebral hemorrhage (3 papers, 2020 to 2022). A cerebrovascular disorder characterized by bleeding into one or both cerebral hemispheres including the basal ganglia and the cerebral cortex. "Previous reports also showed that IL-6 and TNF-α levels increased in TNFAIP3-/- sham groups of an intracerebral hemorrhage mouse model, suggesting that TNFAIP3 deficiency caused spontaneous inflammation in the mouse brain, which was consistent with our results in GMH pups." (PMID 32859236, 2020).
leukemia (3 papers, 2009 to 2025). A malignant (clonal) hematologic disorder, involving hematopoietic stem cells and characterized by the presence of primitive or atypical myeloid or lymphoid cells in the bone marrow and the blood. "In sharp contrast, stem cell gene, Cd34; lineage gene, Gata2; and leukemia stem cell regulator, Ikzf2; as well as Tnfaip3, Pvr (Cd155), and Nectin2 (Cd112), were upregulated in Vav-cre Tet2fl/flTp53fl/fl GMPs." (PMID 40111422, 2025). "Moreover, this study focus on the effects of TNFAIP3 mutation for OS, further studies may include the effects of TNFAIP3 mutation on the disease relapse, treatment‐related mortality (TRM), and leukemia‐free survival (LFS), etc." (PMID 36056685, 2023).
liver cirrhosis (3 papers, 2015 to 2023). "It has also been reported that A20 attenuates liver cirrhosis in nonalcoholic fatty liver disease, and that SNVs in TNFAIP3 are associated with the severity of liver cirrhosis in patients with the human immunodeficiency virus and hepatitis C virus." (PMID 33509297, 2021).
liver disease (3 papers, 2017 to 2025). "Therefore, the potential link between TNFAIP3 polymorphisms and the progression of liver diseases associated with chronic HBV infection needs further investigation in studies of larger sample size of patients." (PMID 28784141, 2017). "Taking into account the role of A20 in HBV infection and liver injury, it is plausible to hypothesize that TNFAIP3 polymorphisms may be relevant to HBV infection and HBV-related liver diseases." (PMID 28784141, 2017). "However, whether these tandem polymorphisms (rs148314165, rs200820567) of TNFAIP3 may affect the susceptibility of chronic HBV infection and HBV-related liver diseases remain unknown." (PMID 28784141, 2017).
major depressive disorder (3 papers, 2019 to 2025). An episode of depression lasting two or more weeks without an intervening episode of mania. "In terms of mental health, TNFAIP3 expression levels are significantly correlated with psychological anxiety symptoms in patients with depression." (PMID 41155519, 2025). "In patients with major depressive disorder, TNFAIP3 mRNA levels were significantly correlated with psychological anxiety symptoms." (PMID 41155519, 2025). "Moreover, a recent clinical study has shown that the mRNA transcription of TNFAIP3, a suppressor of the TLR4 pathway, was inversely correlated with severity of depression and effectively predicted response to antidepressant treatment in major depressive disorder." (PMID 31139084, 2019).
thyroid (3 papers, 2012 to 2024). "The same TNFAIP3 variant was also found in her father who had suffered from recurrent oral aphthosis, vitiligo and thyroiditis since childhood." (PMID 36467491, 2022).
uveitis (3 papers, 2020 to 2024). An inflammatory process affecting a part of or the entire uvea. "Employing real-time quantitative PCR, we found that TNFAIP3 gene expression level was increased in VKH relative to other types of uveitis." (PMID 36301664, 2022). "In addition, TNFAIP3 has been involved in the negative feedback regulation of the inflammatory NF-κB pathway, and its expression is decreased in ocular Behcet’s disease, which is another type of uveitis." (PMID 36301664, 2022).
acute lymphoblastic leukemia (2 papers, 2023 to 2024). Leukemia with an acute onset, characterized by the presence of lymphoblasts in the bone marrow and the peripheral blood. "In acute lymphoblastic leukemia, miR-125b specifically targets tumor necrosis factor-alpha-induced protein 3 (TNFAIP3), which inhibits CD4+ T cell proliferation, boosts glycolysis in T cells, and markedly increases oxygen consumption." (PMID 39007129, 2024).
AIDS (2 papers, 2019 to 2025). A syndrome resulting from the acquired deficiency of cellular immunity caused by the human immunodeficiency virus (HIV). "Variants in TNFAIP3 gene have been described as associated with susceptibility to several AIDs." (PMID 31534975, 2019). "HIV also frequently integrates into lymphocyte activation genes, such as CD5, IL7R, STAT5B, TNFAIP3, and MALT1, which are actively transcribed during immune activation, with higher integration rates in the AIDS group." (PMID 39788938, 2025).
allergic asthma (2 papers, 2022 to 2023). A asthma with a basis in a pathological type I hypersensitivity reaction. "Multiple SNPs of A20/TNFAIP3 are correlated to patients with allergic asthma, AR, and CRS, supporting the notion that the genetic aspect of A20 is critical in allergic airway disorders." (PMID 37056760, 2023). "The autoinflammation-associated NF-κB signaling repressor A20 (TNFAIP3) inhibits airway epithelial cytokine production in response to endotoxin, suppressing type 2 responses to HDM and preventing allergic asthma." (PMID 35281022, 2022).
bipolar disorder (2 papers, 2021 to 2025). A disorder of the brain that causes unusual shifts in mood, energy, activity levels and the ability to carry out day-to-day tasks. "Significantly higher levels TNFAIP3 mRNA levels were found in the monocytes of patients of bipolar disorder." (PMID 34393859, 2021).
Blau syndrome (2 papers, 2021 to 2023). Blau syndrome (BS) is a rare systemic inflammatory disease characterized by early onset granulomatous arthritis, uveitis and skin rash. "In contrast to the understanding that loss-of-function variants of NOD2 were considered nonpathogenic for Blau syndrome, Haploinsufficiency A20 is attributed to loss-of-function variants in TNFAIP3 gene." (PMID 37711606, 2023).
brucellosis (2 papers, 2018 to 2024). Brucellosis is a bacterial infection that spreads from animals to people via unpasteurized dairy products or by exposure to contaminated animal products or infected animals. "In the present study, we investigated the TT>A functional variants, 42 kbp downstream of the TNFAIP3 gene, in our cohort of 1,209 healthy controls and 150 brucellosis patients." (PMID 29343543, 2018). "Further study of the role of this TNFAIP3 gene coding variant in brucellosis is required for a better understanding of how functional genetic variants influence susceptibility to brucellosis." (PMID 29343543, 2018). "A functional study demonstrated that brucellosis patients carrying the protective allele (A) showed significantly lower expression levels of the TNFAIP3 gene in their peripheral blood mononuclear cells and showed increased NF-κB signaling." (PMID 29343543, 2018). "The TT>A variants at the TNFAIP3 gene are important modifiers of the NF-κB signaling pathway, and we hypothesized that the TT>A variants might play a role in the pathogenesis of brucellosis." (PMID 29343543, 2018). "Our findings suggest that a disruption of the normal function of the TNFAIP3 gene might serve as a therapeutic target for the treatment of brucellosis." (PMID 29343543, 2018). "Interestingly, a series of commonly upregulated genes were identified in brucellosis patients, with seven genes/transcription factors (RGS1, DUSP1, FOS, PPP1R15A, TNFAIP3, HLA‐E, and ZFP36) being the most frequent (nine times among nine clusters)." (PMID 39135683, 2024).
Cachexia (2 papers, 2018 to 2020). Severe weight loss, wasting of muscle, loss of appetite, and general debility related to a chronic disease. "To date, no results related to the body weight in conditional TNFAIP3 KO mice are reported, but it has been demonstrated that the germinal deletion of TNFAIP3 induces cachexia." (PMID 32325694, 2020). "A20/TNFAIP3 is critical in inflammation regulation, as mice with germ-line A20/Tnfaip3-deletion developed severe multiorgan inflammation and cachexia, resulting in early death." (PMID 29515565, 2018).
colon cancer (2 papers, 2018 to 2020). "Although the function of miR-29c expression in colon cancer has not been clarified, miR-29c exhibits a tumor suppressor function in several types of cancer by targeting TNFAIP3 and cyclin E, thereby inhibiting tumorigenesis and metastasis." (PMID 29651113, 2018).
cystic fibrosis (2 papers, 2017 to 2022). Autosomal recessive disorder caused by pathogenic variants in the CFTR gene (cystic fibrosis transmembrane conductance regulator), which encodes a chloride and bicarbonate channel expressed in epithelial cells, and follow the diagnosis criteria. "Interestingly we also found two cystic fibrosis modifier genes, ANO1 (TMEM16A) and TNFAIP3, downregulated by 60% and 70% respectively, in CNP-exposed cells." (PMID 35995803, 2022).
dermatitis (2 papers, 2019 to 2020). An inflammatory process affecting the skin. "Similarly, other studies reported that the severity of skin inflammation in epidermis-specific TNFAIP3-knockout mice was exacerbated and associated with the upregulation of proinflammatory cytokines and chemokines." (PMID 32280718, 2020). "Our data support the idea that TNF-α antagonists attenuate skin inflammation and increase TNFAIP3 expression accompanied by the downregulation of Th1- and Th17-related cytokines and phosphorylated p38 levels." (PMID 32280718, 2020). "Likewise, human studies indicate that low TNFAIP3 expression reduces the threshold for dermatitis in psoriatic patients, whereas external factors such as infections and trauma are necessary to induce psoriatic lesions." (PMID 31120955, 2019). "Interestingly, TNFAIP3 haplo-insufficient mice that were not exposed to inflammatory stimuli have not developed apparent dermatitis." (PMID 31120955, 2019).
Epstein-Barr virus infection (2 papers, 2021 to 2023). An infection that is caused by Epstein-Barr virus. "LPINI involved in alcoholic liver disease and TNFAIP3 mainly related to Epstein-Barr virus infection, measles, necroptosis, NOD-like receptor signaling pathway and TNF signaling pathway." (PMID 36918862, 2023).
esophageal cancer (2 papers, 2021 to 2026). A primary or metastatic malignant neoplasm involving the esophagus. "RP11-356I2.4 (also known as WAKMAR2, lnc-TNFAIP3, or LOC100130476) has been shown to act as a tumor suppressor gene in esophageal cancer and gastric cardia adenocarcinoma." (PMID 34367239, 2021).
follicular lymphoma (2 papers, 2013 to 2022). Follicular lymphoma is a form of non-Hodgkin lymphoma characterized by a proliferation of B cells whose nodular structure of follicular architecture is preserved. "In addition, each contingent showed its own pathogenic variants, such as BCL2, KMT2D, EP300 in the follicular lymphoma contingent, and XPO1, TNFAIP3, and CREBBP in the cHL contingent." (PMID 36428786, 2022).
hyperlipidaemia (2 papers, 2020 to 2025). "Our results also suggest that hyperlipidaemia contributes to alteration in early immature cDC1 and in the abundance of late immature cDC1 cells, which was associated with dramatic change in gene expression of Tnfaip3, Serinc3, Apol7c, and Tifab." (PMID 40934103, 2025).
ischemia (2 papers, 2025). A hypoperfusion of the BLOOD through an organ or tissue caused by a PATHOLOGIC CONSTRICTION or obstruction of its BLOOD VESSELS, or an absence of BLOOD CIRCULATION. "The expression of TNFAIP3 was significantly up-regulated in Kupffer cell population after reperfusion, which may have a protective effect on ischemia-reperfusion injury." (PMID 40718477, 2025). "Previous studies have shown that TNFAIP3 activates the Hippo-YAP signaling pathway, which is involved in mitigating hepatic ischemia-reperfusion injury." (PMID 41296787, 2025).
keloid (2 papers, 2023 to 2024). An irregularly shaped, elevated mark on the skin caused by deposits of excessive amounts of collagen during wound healing. "Five hub genes were linked to keloid recurrence, including CHI3L1, IL1RN, MMP7, TNFAIP3, and TNFAIP6." (PMID 37685578, 2023). "IL-17A, TNFAIP3, and CCL20 were found to be significantly increased in the keloid Th17 cells compared to the healthy skin Th17 cells." (PMID 39872534, 2024). "In the present study, the hub genes (CHI3L1, IL1RN, MMP7, TNFAIP3, and TNFAIP6) were mainly involved in the regulation of inflammatory response, IL-17 signalling pathway, and TNF signalling pathway, which is consistent with previous findings in keloids." (PMID 37685578, 2023). "The qRT-PCR experiment was used for detecting the differential expression of five hub genes (CHI3L1, IL1RN, MMP7, TNFAIP3, and TNFAIP6) in recurrent and non-recurrent keloid tissues." (PMID 37685578, 2023).
lung adenocarcinoma (2 papers, 2020 to 2026). A carcinoma that arises from the lung and is characterized by the presence of malignant glandular epithelial cells. "TNFAIP3 expression was significantly downregulated (p < 0.001, Wilcoxon test) in breast invasive carcinoma (BRCA) and 11 other cancer types, including lung adenocarcinoma (LUAD), colon adenocarcinoma (COAD), and bladder urothelial carcinoma (BLCA)." (PMID 41461391, 2026).
lymph node metastasis (2 papers, 2021 to 2022). "The TNFAIP3 and NFκB protein expressions were significantly associated with lymph node metastasis and tumor differentiation (P < 0.05)." (PMID 36033828, 2022).
measles (2 papers, 2023). A highly contagious viral infection caused by the measles virus. "Transcriptomic analysis of peripheral blood mononuclear cells (PBMCs) from children with measles shows upregulation of mRNAs for IL-1β, CIAS-1/NLRP3, tumor necrosis factor (TNF)α, CCL4/MIP-1β, CXCL2/GRO-β, CXCL8, and TNFAIP3/A20 consistent with NF-κB signaling and inflammasome priming." (PMID 36851476, 2023).